GTF2H5 (general transcription factor IIH subunit 5)
Description:
Component of the general transcription and DNA repair factor IIH (TFIIH) core complex, which is involved in general and transcription-coupled nucleotide excision repair (NER) of damaged DNA and, when complexed to CAK, in RNA transcription by RNA polymerase II. In NER, TFIIH acts by opening DNA around the lesion to allow the excision of the damaged oligonucleotide and its replacement by a new DNA fragment. In transcription, TFIIH has an essential role in transcription initiation. When the pre-initiation complex (PIC) has been established, TFIIH is required for promoter opening and promoter escape. Phosphorylation of the C-terminal tail (CTD) of the largest subunit of RNA polymerase II by the kinase module CAK controls the initiation of transcription. Necessary for the stability of the TFIIH complex and for the presence of normal levels of TFIIH in the cell.
Synonyms: C6orf175; TTDA; FLJ30544; bA120J8.2; TTD-A; TFB5; TFIIH; TGF2H5; TTD; TTD3
Tractability: Small molecule: a structure with a bound ligand is known. PROTAC: ubiquitination databases record sites on it.
Gene: Protein-coding gene on chromosome 6 (158,168,338 to 158,199,344, forward strand). Ensembl gene ENSG00000272047.
Subcellular location: Nucleus; Cytoplasm
Pathways (Reactome):
Gene expression (Transcription): Formation of RNA Pol II elongation complex; Formation of the Early Elongation Complex; NoRC negatively regulates rRNA expression; RNA Pol II CTD phosphorylation and interaction with CE; RNA Polymerase I Promoter Escape; RNA Polymerase I Transcription Initiation; RNA Polymerase I Transcription Termination; RNA Polymerase II Pre-transcription Events; RNA Polymerase II Promoter Escape; RNA Polymerase II Transcription Elongation; RNA Polymerase II Transcription Initiation; RNA Polymerase II Transcription Initiation And Promoter Clearance; RNA Polymerase II Transcription Pre-Initiation And Promoter Opening
Disease: Formation of HIV elongation complex in the absence of HIV Tat; Formation of HIV-1 elongation complex containing HIV-1 Tat; Formation of the HIV-1 Early Elongation Complex; HIV Transcription Initiation; RNA Pol II CTD phosphorylation and interaction with CE during HIV infection; RNA Polymerase II HIV Promoter Escape; Tat-mediated elongation of the HIV-1 transcript; Transcription of the HIV genome
DNA Repair: Dual Incision in GG-NER; Dual incision in TC-NER; Formation of Incision Complex in GG-NER; Formation of TC-NER Pre-Incision Complex; Gap-filling DNA repair synthesis and ligation in TC-NER; Transcription-Coupled Nucleotide Excision Repair (TC-NER)
Metabolism of RNA: mRNA Capping
Gene Ontology:
Molecular function: protein binding
Biological process: nucleotide-excision repair; nucleotide-excision repair, preincision complex assembly; transcription by RNA polymerase II; transcription initiation at RNA polymerase II promoter
Cellular component: nucleolus; nucleus; transcription factor TFIID complex; transcription factor TFIIH holo complex; cytoplasm; nucleoplasm; transcription factor TFIIH core complex
Genetic constraint (gnomAD): Loss-of-function variants: 5 observed, 5.57 expected, observed/expected ratio (o/e) 0.9, 90% interval 0.46 to 1.73. That is too few expected variants to judge how well the gene tolerates losing a copy. Missense variants: 69 observed, 71.99 expected, observed/expected ratio (o/e) 0.96, 90% interval 0.79 to 1.17. Synonymous variants: 22 observed, 27.38 expected, observed/expected ratio (o/e) 0.8, 90% interval 0.57 to 1.15.
Homologues: Orthologues: chimpanzee GTF2H5 (100% identical), dog GTF2H5 (100% identical), macaque GTF2H5 (100% identical), rabbit GTF2H5 (100% identical), rat Gtf2h5 (100% identical), guinea pig GTF2H5 (99% identical), mouse Gtf2h5 (99% identical), pig GTF2H5 (89% identical), rat LOC120103497 (83% identical), tropical clawed frog gtf2h5 (83% identical), zebrafish gtf2h5 (83% identical), Drosophila melanogaster Tfb5 (65% identical), and 1 more.
Diseases named in the same sentence as GTF2H5 in open-access papers:
GTF2H5 is named in the same sentence as 25 diseases in open-access papers, as found by Europe PMC text mining. Sharing a sentence is not in itself a finding about the gene and the disease. The quoted sentences say what the papers report.
trichothiodystrophy (10 papers, 2005 to 2025). Trichothiodystrophy or TTD is a heterogeneous group disorders characterized by short, brittle hair with low-sulphur content (due to an abnormal synthesis of the sulfur containing keratins). "Hereditary mutations in its smallest subunit, TTDA/GTF2H5, cause a photosensitive form of the rare developmental disorder trichothiodystrophy." (PMID 34824371, 2021). "Hereditary mutations in TTDA/GTF2H5 cause a photosensitive form of the rare developmental disorder trichothiodystrophy, however the development of models has been hampered by mutations being lethal." (PMID 34824371, 2021). "This rare mutation (Leu21Pro) occurs in the gene GTF2H5, a transcription factor involved in DNA repair, and causes trichothiodystrophy resulting in patients with brittle hair and nails, due to a reduced content of cysteine-rich matrix proteins." (PMID 17708757, 2007). "The gene GTF2H5, participating in the interstrand adducts removal process of DNA repair, was reported to be associated with mastitis and lipomatous myopathy in cattle, lentivirus susceptibility in sheep, ovarian cancer, and trichothiodystrophy in human." (PMID 33719343, 2021). "Among these disorders are Cockayne syndrome which is caused by mutations in ERCC6 (CSB) or ERCC8 (CSA), trichothiodystrophy (TTD) caused by mutations in ERCC2 (XPD), ERCC3 (XPB), or TTDA (GTF2H5) and XPF-ERCC1 progeria (XFE) caused by dysfunction of the XPF-ERCC1 heterodimer." (PMID 23947592, 2013).
ovarian carcinoma (3 papers, 2019 to 2022). A malignant neoplasm originating from the surface ovarian epithelium. "XPC, SMUG1, and GTF2H5 were the top 3 most significant genes associated with ovarian cancer survival according to the prognostic signature." (PMID 31572446, 2019). "GTF2H5, BICD1, and CLK3 have been reported to be oncogenes in ovarian cancer and hepatocellular carcinoma and are strongly associated with prognosis." (PMID 36212157, 2022).
Ataxia (1 paper, 2020). Ataxia refers to impaired coordination of voluntary muscle movement. "We, therefore, supplemented the EOAD- control group with ataxia genotypes that were not reported with comorbid dystonia in literature (including ABHD12; IFRD1; KIAA0226; PHYH; TDP1; VWA3B; GTF2H5; FLVCR1; ACO2; HSD17B4; DNAJC3 gene mutations; PubMed and OMIM)." (PMID 33255407, 2020).
colon cancer (1 paper, 2022). "Our findings indicated that DEDD2, GTF2H5, SNRPA1, BICD1, CELF1, and CLK3 were prognostic risk factors for colon cancer, while ADAD1, CMTR1, HNRNPUL1, FTSJ3, WDR43, THUMPD3, SNRPF were prognostic protective factors." (PMID 36212157, 2022).
intrauterine growth restriction (1 paper, 2023). "Whole exome sequencing for a male neonate with premature rupture of membranes and intrauterine growth restriction showed that GTF2H5 gene mutations induced severe clinical manifestations including multiple-organ failure." (PMID 36833449, 2023).
melanoma (1 paper, 2021). A malignant, usually aggressive tumor composed of atypical, neoplastic melanocytes. "In melanoma brain metastases, heterozygous copy number loss of HR and SSB repair, but no mismatch repair-associated genes, was found, which from the most prevalent genes were APTX, FEN1, GTF2H5, DNA2, MUS81 and TOP3A." (PMID 34885093, 2021).
oral cancers (1 paper, 2013). "Since genes involved in DNA repair functions are commonly associated with oral cancer, it is very likely that GTF2H5 is also related to carcinogenesis." (PMID 24007313, 2013).
serous ovarian cancer (1 paper, 2025). "Involved in nucleotide excision repair (NER), GTF2H5 has been shown to predict survival in high-grade serous ovarian cancer." (PMID 41375077, 2025).
GTF2H5 also shares sentences with these, for which no sentence is quoted: Cockayne syndrome (5 papers); xeroderma pigmentosum (5); tumor (2); asthma (1); developmental disabilities (1); Dystonia (1); eczema (1); hepatocellular carcinoma (1); ichthyosis (1); infection (1); Insulin resistance (1); lung carcinoma (1); mastitis (1); Multiple Organ Failure (1); photosensitive trichothiodystrophy-3 (1); preeclampsia (1); progeria (1).